SYP (synaptophysin)
Diseases named in the same sentence as SYP in open-access papers (continued):
Sharing a sentence is not in itself a finding about the gene and the disease.
cholangiocarcinoma (2 papers, 2010 to 2019). A carcinoma that arises from the intrahepatic biliary tree (intrahepatic cholangiocarcinoma) or from the junction, or adjacent to the junction, of the right and left hepatic ducts (hilar cholangiocarcinoma). "Five hepatic carcinoids (11%) positive for one or more neuro-endocrine differentiation markers (chromogranin-A, neuron-specific enolase, and synaptophysin) and three cholangiocellular carcinomas (7%) were not further analysed in this study." (PMID 20167095, 2010).
choroid plexus papilloma (2 papers, 2014 to 2025). "Synaptophysin immunoreactivity is described in normal choroid plexus epithelium and in choroid plexus papillomas and carcinomas, though expression is variably present (not always strong or diffuse)." (PMID 41220478, 2025).
clear cell carcinoma (2 papers, 2008 to 2025). "Furthermore, strong positivity for neuroendocrine markers synaptophysin and chromogranin reliably excluded clear cell carcinoma in this case." (PMID 41149460, 2025). "Diagnosis of clear cell carcinoma was based on certain histological characteristics of the tumour and immunohistochemical analysis (PAS staining, keratins AE1/AE3, EMA, cytokeratin 7, cytokeratin 20, melanosomes, vimentin, Chromogranin, Synaptophysin, S-100, SMA)." (PMID 18442419, 2008).
colitis (2 papers, 2023 to 2026). Inflammation of the colon. "The colitis-induced reductions in presynaptic SYP and postsynaptic PSD95 expression, critical markers of synaptic density, were fully rescued by AmEVs treatment." (PMID 41496520, 2026). "As a final assessment of colitis- and probiotic-mediated changes in the brain, we examined the protein levels of post synaptic density protein 95, (PSD95) and synaptophysin to quantify postsynaptic and presynaptic compartment integrity, respectively." (PMID 37511312, 2023).
colon cancer (2 papers, 2019 to 2021). "However, CD44, NCAM1,SYP, and NCAPG showed higher expression levels than NCM-460 in the majority of colon cancer cell lines." (PMID 35155186, 2021).
dementia with Lewy bodies (2 papers, 2014 to 2023). "More important the loss of synaptophysin has been describe in neurodegenerative disease such, dementia with Lewy bodies, AD, PD and other." (PMID 38042807, 2023). "Moreover, transplantation of GDAsBMP also increased levels of synaptophysin, a widely used marker of synaptic density that is decreased in Lewy body diseases like PD and that has not been addressed by other approaches." (PMID 24477866, 2014).
diabetic retinopathy (2 papers, 2011 to 2021). "Reduction in synaptophysin expression was also seen in other experimental retinopathy models (streptozotocin-induced diabetic retinopathy and bilateral common carotid artery occlusion-induced ischemic retinopathy)." (PMID 33799938, 2021). "The reduction of synaptophysin levels and neuronal activity, observed 1 month after the onset of diabetic retinopathy, is later followed by the apoptosis of retinal ganglion cells and inner retinal cells." (PMID 21076532, 2011). "In diabetic retinopathy, angiotensin II type 1 receptor (AT1R) signaling activates ERK in the inner layers of the retina, causing UPS-mediated excessive degradation of the synaptic vesicle protein, synaptophysin." (PMID 21076532, 2011). "ERK activation and the resulting reduction of synaptophysin in the diabetic retina is also inhibited by an antioxidant, lutein, which indicates that angiotensin II signaling and oxidative stress may share a role in the pathogenesis of diabetic retinopathy." (PMID 21076532, 2011).
gastric cancer (2 papers, 2022 to 2023). A primary or metastatic malignant neoplasm involving the stomach. "Catecholamines upregulate metastasis‐associated in colon cancer 1 (MACC1), which binds directly to synaptophysin (SYP) via the β2-AR/c-Jun signaling pathway, thereby promoting the neuroendocrine phenotypic transformation of gastric cancer cells and accelerating metastasis." (PMID 36707854, 2023). "Therefore, we examined the two gastric cancer cells for ECL markers chromogranin A (CgA) and synaptophysin (Syn) by immunocytochemistry and immunofluorescence, and negative staining was observed for CgA and Syn in both SGC-7901 and AGS cells." (PMID 34976177, 2022).
hemorrhagic stroke (2 papers, 2021 to 2022). A stroke caused by a bleed on the brain. "However, 14 days after hemorrhagic stroke, both SYP+ and Homer-1+ proteins were engulfed by microglia/macrophages but few were engulfed by astrocytes." (PMID 34836962, 2021). "The combined therapy increased the expression of synapse-associated proteins (SYP and PSD95), and the results suggest that the protective effects of the combined therapy on mTOR may be related to its ability to increase synaptic plasticity in the hemorrhagic stroke." (PMID 35211177, 2022). "Similarly, 14 days after hemorrhagic stroke, microglia/macrophage-specific MEGF10KO or MERTKKO mice also exhibited fewer Homer-1+ and SYP+ synaptic puncta in microglia/macrophages than control mice." (PMID 34836962, 2021).
hepatocellular carcinoma (2 papers, 2017 to 2022). A malignant tumor that arises from hepatocytes. "Histopathological work-up revealed poorly differentiated hepatocellular carcinoma (Edmondson-Steiner grade IV) with diffuse expression of neuroendocrine markers synaptophysin and chromogranin." (PMID 35789568, 2022).
HIV-1 infection (2 papers, 2022 to 2023). The type species of lentivirus and the etiologic agent of acquired immunodeficiency syndrome (AIDS). "HIV-1 infection causes synaptodendritic injury, and decreased SYP and MAP2 biomarkers have been associated with higher viral load and impaired cognitive function in HAND105." (PMID 35301411, 2022). "In addition, loss of synaptophysin was observed in HIV-1 infection in humanized mice and exposure to HIV-1 proteins, like Tat and gp120, markedly decreased PSD95 in hippocampal neurons." (PMID 37458985, 2023).
Insulin resistance (2 papers, 2021). Increased resistance towards insulin, that is, diminished effectiveness of insulin in reducing blood glucose levels. "We found that the reduction of synaptophysin, as well as other relevant synaptic proteins also occurs in db/db mouse, a type 2 diabetic model with hyperinsulinemia and insulin resistance." (PMID 34944588, 2021).
neuroendocrine neoplasms of the pancreas (2 papers, 2020 to 2022). "Common to neuroendocrine neoplasms of the pancreas is their expression of synaptophysin, chromogranin A, and/or INSM1." (PMID 34647171, 2022).
Neuroendocrine prostate carcinoma (2 papers, 2020 to 2023). "Neuroendocrine prostate carcinoma (NEPC) is recognized by neuroendocrine markers such as chromogranin A (CgA), synaptophysin (Syn), and neuron-specific enolase (NSE)." (PMID 38077153, 2023). "The CDX also expresses a neuroendocrine phenotype positive for synaptophysin, chromogranin, NSE, and absence of PSA and AR, and reflects the functional state of neuroendocrine prostate carcinoma in being unresponsive to androgen deprivation." (PMID 32313004, 2020).
non-small cell lung carcinoma (2 papers, 2010 to 2021). A group of at least three distinct histological types of lung cancer, including non-small cell squamous cell carcinoma, adenocarcinoma, and large cell carcinoma. "Therefore, we investigated retrospectively a large cohort to expand the data on the role of synaptophysin, chromogranin and CD56 in non-small cell lung cancer lacking morphological features of neuroendocrine differentiation." (PMID 33933015, 2021).
NUT carcinoma (2 papers, 2021 to 2024). "Synaptophysin was positive by immunohistochemical analysis for some NUT carcinoma cases; however, no cases were positive for chromogranin A or CD56." (PMID 38326851, 2024).
olfactory neuroblastoma (2 papers, 2013 to 2019). An olfactory neuroblastoma arising in the paranasal sinus. "Olfactory neuroblastomas frequently express NSE and synaptophysin and are negative for the expression of leucocyte common antigen and CD99." (PMID 31531255, 2019).
ovarian neoplasm (2 papers, 2025). A benign, borderline, or malignant neoplasm involving the ovary. "This highlights the importance of assessing neuroendocrine markers, such as chromogranin A, synaptophysin, and Ki-67; when evaluating atypical ovarian tumors biologically, O-NENs encompass a wide spectrum of behaviors." (PMID 41464736, 2025). "Immunohistochemical markers such as synaptophysin, chromogranin A, and CD56 remain critical for accurate diagnosis and differentiation from other ovarian neoplasms." (PMID 40490785, 2025).
pancreatic ductal adenocarcinoma (2 papers, 2017 to 2024). An infiltrating adenocarcinoma that arises from the epithelial cells of the pancreas. "We analyzed ductal and neuroendocrine markers in pancreatic ductal adenocarcinoma, revealing heterogeneous expression of the neuroendocrine marker Synaptophysin within ductal lesions." (PMID 29170413, 2017). "We observe similar lineage marker heterogeneity in mouse models of pancreatic ductal adenocarcinoma, where lineage tracing indicates that Cytokeratin-Synaptophysin dual positive cells arise from the exocrine compartment." (PMID 29170413, 2017).
prostate small cell carcinoma (2 papers, 2021 to 2023). A neuroendocrine carcinoma of the prostate gland with unfavorable prognosis, composed of small cells containing neurosecretory granules. "One case was small cell neuroendocrine carcinoma of the prostate and was positive for chromogranin A (CGA), synaptophysin (SYN), and cluster of differentiation 56 (CD56)." (PMID 37576903, 2023).
retinal degeneration (2 papers, 2012 to 2014). Degeneration of the retina. "To further confirm our finding, we measured synaptophysin levels in another animal model of retinal degeneration where photoreceptor degeneration was induced in adult wild-type mouse using N-Methyl-N-nitrosourea (MNU)." (PMID 24595229, 2014).
retinoblastoma (2 papers, 2009 to 2025). A malignant tumor that originates in the nuclear layer of the retina. "Finally we find that CRX is a new sensitive and specific marker for retinoblastoma and pineal parenchymal tumors that should be useful in the diagnostic evaluation of pineal masses when used as part of a panel of immunohistochemical markers including synaptophysin and GFAP." (PMID 19936203, 2009).
sarcomatoid carcinoma (2 papers, 2011 to 2013). A malignant epithelial neoplasm characterized by the presence of spindle cells and anaplastic morphologic features. "To include LCNEC, we expanded our antibody panel not only with vimentin, which can serve as a marker for sarcomatoid carcinoma, but also with neurendocrine markers (CD56, Synaptophysin, Chromogranin A)." (PMID 23418554, 2013). "In this study, we reported strong positivity for synaptophysin detected in the RMS component of one of the sarcomatoid carcinomas, which was not reported previously." (PMID 21762516, 2011).
viral infection (2 papers, 2023 to 2025). "Synaptophysin IHC did not reveal any viral infection of neuroendocrine cells." (PMID 36851589, 2023).
adrenal neuroblastoma (1 paper, 2019). "Microscopic and immunohistochemical staining, which were positive for synaptophysin, CD56, and vimentin, confirmed the diagnosis of adrenal neuroblastoma." (PMID 31500669, 2019).
age-related macular degeneration (1 paper, 2020). Age-related loss of vision in the central portion of the retina (macula), secondary to retinal degeneration. "In an animal model of age-related macular degeneration, the expression of the synapse-associated proteins synaptophysin and VGluT1 was significantly diminished." (PMID 32977518, 2020).
ameloblastoma (1 paper, 2025). The most common odontogenic tumor, arising from the epithelial component of the embryonic tooth and usually affecting the molar-ramus region of the mandible or maxilla. "Considering the known functions of CLU, our results suggest that it is closely linked to the differentiation of a subset of ameloblastoma cells into neuroendocrine-like cells that express SYP and INSM1." (PMID 39937015, 2025). "We examined neuroendocrine markers, including CD56, SYP, and CgA, in 36 ameloblastomas and identified five specimens that exhibited the immunoexpression of CD56 and SYP, suggesting neuroendocrine differentiation in ameloblastomas." (PMID 39937015, 2025). "Immunohistochemically, ameloblastomas often express CD56; however, novel neuroendocrine markers such as synaptophysin (SYP), insulinoma-associated protein 1 (INSM1), and chromogranin A (CgA) remain unexplored." (PMID 39937015, 2025). "This study is the first to suggest neuroendocrine differentiation in ameloblastomas, as indicated by SYP and INSM1 immunoexpression and the presence of dense-core granules, which are consistent with the recent World Health Organization classification of Head and Neck Tumors guidelines." (PMID 39937015, 2025). "Additionally, the immunoexpression of INSM1, a second-generation neuroendocrine marker, in SYP-positive ameloblastomas further supports this finding, along with the ultrastructural presence of dense-core granules." (PMID 39937015, 2025). "This study is the first to suggest neuroendocrine differentiation in a small subset of ameloblastomas, characterized by SYP positivity and CgA negativity, along with INSM1 immunoexpression, in line with the recent understanding of neuroendocrine characteristics in the WHO classification." (PMID 39937015, 2025). "SYP-positive and CgA-negative phenotypes may characterize neuroendocrine differentiation in ameloblastoma." (PMID 39937015, 2025). "Given the recent understanding of neuroendocrine characteristics, the immunoexpression of SYP and INSM1 in a limited number of tumor cells in this study signifies genuine neuroendocrine differentiation in ameloblastomas." (PMID 39937015, 2025). "The ectopic expression of SYP and INSM1 in ameloblastomas seems to be a unique example of SYP and INSM1 expression." (PMID 39937015, 2025). "We analyzed 36 ameloblastoma specimens for CD56, SYP, CgA, and clusterin (CLU) and examined limited samples for INSM1 expression by performing immunohistochemistry, transmission electron microscopy, and reverse transcriptase-polymerase chain reaction." (PMID 39937015, 2025). "Therefore, first of all, we investigated the nature of ameloblastomas using the classic and revised neuroendocrine markers, CD56, SYP, CgA, and INSM1, as well as the correlation between CLU and the expression of neuroendocrine markers." (PMID 39937015, 2025).
anaplastic large cell lymphoma (1 paper, 2022). Anaplastic large cell lymphoma (ALCL) is a rare and aggressive peripheral T-cell non-Hodgkin lymphoma, belonging to the group of CD30-positive lymphoproliferative disorders, which affects lymph nodes and extranodal sites. "Immunohistochemical staining of synaptophysin was performed in 59 diagnosed cases of classic Hodgkin lymphoma, 10 anaplastic large cell lymphomas, 16 diffuse large B-cell lymphomas, and 5 extranodal marginal zone lymphoma of the mucosa-associated tissue." (PMID 36401284, 2022). "None of the anaplastic large cell lymphomas expressed synaptophysin." (PMID 36401284, 2022). "It was an unexpected, novel finding that synaptophysin was not expressed in other reactive hematolymphoid cells in the background, even in cases of CD30-positive anaplastic large cell lymphoma (ALCL), diffuse large B-cell lymphoma (DLBCL) with B-cell lineage, and MALT lymphoma." (PMID 36401284, 2022).
angina pectoris (1 paper, 2015). The symptom of paroxysmal pain consequent to MYOCARDIAL ISCHEMIA usually of distinctive character, location and radiation. "The overexpression of synaptophysin- and Fos-immunoreactivity and the potentiated excitatory pre- and postsynaptic transmission strongly indicate that NTS sensitization may be significantly involved in angina pectoris caused by chronic occlusion of the coronary artery." (PMID 25756354, 2015).
bacterial sepsis (1 paper, 2021). "There are few studies that correlate infection during gestation and disturbance of synaptophysin expression in the offspring and none using bacterial sepsis models." (PMID 33632243, 2021).
basaloid carcinoma (1 paper, 2017). A malignant epithelial neoplasm characterized by the presence of neoplastic cells with hyperchromatic nuclei, small amount of cytoplasm, and peripheral nuclear palisading. "Basaloid carcinoma usually expresses p63 and p40, rarely CD5 and CK5/6, but is negative for neuroendocrine markers like synaptophysin and chromogranin." (PMID 28602157, 2017).
bipolar disorder (1 paper, 2020). A disorder of the brain that causes unusual shifts in mood, energy, activity levels and the ability to carry out day-to-day tasks. "A previous study found that levels of the excitatory presynaptic membrane protein synaptophysin are reduced in frontal cortex samples from patients with bipolar disorder." (PMID 33109198, 2020).
Brain atrophy (1 paper, 2015). Partial or complete wasting (loss) of brain tissue that was once present. "However, unlike the terminal cases, there was no brain atrophy or significant differences in CSPα or synaptophysin in the neuropil compared to the controls." (PMID 26610600, 2015).
carcinoid syndrome (1 paper, 2014). "In the responders with NET that had carcinoid syndrome with flushing and diarrhea, nelfinavir improved these symptoms within 7 days, which was associated with transient decreases in levels of circulating chromogranin, synaptophysin, and/or urinary 5-HIAA." (PMID 25327558, 2014).
carcinoma in situ (1 paper, 2020). "Biopsy was consistent with primary SCCB that was poorly differentiated, positive for synaptophysin and chromogranin and TTF-1 and presence of ductal carcinoma in situ component showing neuroendocrine differentiation." (PMID 32411090, 2020).
cardiac arrest (1 paper, 2025). Cessation of breathing and/or cardiac function. "In mouse models of cardiac arrest-induced neuronal death, tDCS enhanced expression of proteins related to synaptic function and regeneration, including MAP2, GAP43, PSD95, and synaptophysin." (PMID 41440017, 2025).
cerebellar tumor (1 paper, 2020). "Additional CNS HGNET-BCOR cerebellar tumor, originally diagnosed as unclassified malignant neuroepithelial tumor, showed lack of exon 15 of BCOR gene duplication and negative reaction for GFAP and synaptophysin." (PMID 32650833, 2020).
chemodectoma (1 paper, 2023). "Synaptophysin and chromogranin A were the most useful immunohistochemical markers to diagnose malignant chemodectoma in this cat." (PMID 37533454, 2023).
chordoma (1 paper, 2021). Chordomas are rare malignant tumors arising from embryonic remnants of the notochord in axial skeleton. "The complete absence of chromograninA should always arouse suspicion against the diagnosis of NEC/NET, as was seen in the chordoma case, which ran for years under the diagnosis of a metastasized NET based on a positive synaptophysin staining only, never accompanied by any chromograninA labeling." (PMID 34350470, 2021).
chronic hepatitis (1 paper, 2006). An active inflammatory process affecting the liver for more than six months. "In a frozen chronic hepatitis case (with expected activated hepatic MF and HSC), HSC were negative to synaptophysin, GFAP and NCAM." (PMID 17109742, 2006). "In the frozen chronic hepatitis case (with expected activated hepatic MF and HSC), only nerves in larger portal areas reacted positively to GFAP and NCAM, while synaptophysin did not provoke any signal at all." (PMID 17109742, 2006).
congenital heart disease (1 paper, 2025). A heart disease that is present at birth. "In three cases (including the case with congenital heart disease), small nodules of neurons in the periventricular region and subcortical white matter were highlighted with NeuN and synaptophysin, in keeping with small heterotopia and representing a neuronal migration defect." (PMID 40299318, 2025).